IFNG (interferon gamma)
Diseases named in the same sentence as IFNG in open-access papers (continued):
Sharing a sentence is not in itself a finding about the gene and the disease.
tumor (continued). "To further determine the role of IL-4 in adaptive immune evasion, we studied cancer cell killing in co-cultures of A549 cells with tumor antigen-specific CD8+ T-cells with or without exposure to IL-4 and/or IFNγ + TNFα." (PMID 40091029, 2025). "In parallel, RMC tumor cells upregulated expression of IFNGR1, which normally engages IFNγ to activate proliferation of myeloid lineage immune cells via the MAPK signaling pathway as part of the innate immune response." (PMID 41290625, 2025). "In OSCC, the expression level of the lncRNA CRNDE is significantly elevated within tumor-infiltrating CD8+ T cells and shows a negative correlation with interferon-gamma (IFN-γ) production." (PMID 41221298, 2025). "Laboratory tests demonstrated elevated C-reactive protein (4.75 mg/dL), but some tumor markers (including CEA, CA19-9, and CA125), anti-nuclear antibodies, MPO-ANCA, PR3-ANCA, β-D-glucan, and interferon-gamma release assay were all negative." (PMID 40870884, 2025). "Researchers found that SEMA6D is predominantly expressed by non-hematopoietic cells, especially tumor cells, and shows a strong negative correlation with CD8A, PDCD1, IFNG and GZMB." (PMID 41438751, 2025). "Stimulation of PBMC with 1B3-transfected tumor cells alone did not result in activation of CD4+ or CD8+ T cells, but CD4-CD8- T cells did show an increase in percentage IFNγ+ and TNFα+ cells suggesting that this population can respond to tumor cells directly." (PMID 39007281, 2024). "Mice treated with the Ace-Resi group demonstrated increased frequencies and counts of CD8+ T cells, interferon gamma (IFNγ+) CD8+ T cells, and polyfunctional IFNγ+ GzmB+ CD8+ T cells compared to naïve tumor-bearing mice and healthy (no tumor) controls." (PMID 39399681, 2024). "sMIC expression also significantly impaired tumoral CD8 T cell response to PMA/I stimulation as measured by IFNγ expression (p < 0.05 in all models); however, CD8 T cell content in tumor infiltrates was not significantly impacted by sMICB." (PMID 38255301, 2024). "The source of IFNγ is likely T cells, as depletion of NK cells did not restore growth of 9609‐MEK1‐hi tumours." (PMID 39330930, 2024). "In mice lacking Dock2, IFNγ production is increased in multiple T cell populations, including CD8+ and γδ T cells, and administrating IFNγ to tumour organoids induces robust IDO1 expression suggesting this response is driven by immune cell IFNγ production." (PMID 39242821, 2024). "We observed specific release of IFNg, GranzymeB and Perforin upon anti-CD3 + IL2 treatment and not upon LPS treatment for the same tumor sample." (PMID 38383563, 2024). "As zebularine enhanced the immunogenicity of tumor cells by transcriptionally inducing MHC-AgPPM genes, which is independent of IFNγ signaling, we found that promoting MHC-AgPP is mainly dependent on type I interferon and facilitated by IFNγ." (PMID 38755254, 2024). "Further characterization of the tumor cells revealed granzyme B activity in HROC113 as well as HROC285 T0 M2, which was found independent of IFNγ treatment." (PMID 39075115, 2024). "Here, we discovered that attIL12 modification of TILs synergizes IFNγ production in tumors (but not in peripheral tissues), enhances TIL infiltration into autologous collagen-rich PDX tumors, and inhibits tumor progression." (PMID 39574893, 2024). "Even if other immune cells such as NK-cells or CD4+ cells can also produce IFNγ, a depletion of these cell types, in contrast to CD8+ T-cell depletion, did not lead to a reversal of the tumour growth reduction." (PMID 38271469, 2024). "The strength of the IFNγ response mounted against E7 was comparable to the nonspecific response induced by the Protein Kinase C (PKC) activator and potent tumor promoter phorbol 12-myristate 13-acetate (PMA) stimulation." (PMID 37503351, 2023).
tumor (continued). "Anti-SLAMF4 mAb therapy of mouse NK cells results in increased interferon-gamma (IFN-γ) production and non-major histocompatibility complex (MHC)-restricted tumor cell killing in vitro." (PMID 37251372, 2023). "Although data on cytolytic anti-tumor activity of the transferred CD4+ T cells was not provided, release of the effector cytokine IFNγ was demonstrated." (PMID 37965314, 2023). "Furthermore, chronic tumor exposure had a negative impact on general NK-cell anti-tumor function, resulting in reduced degranulation and decreased expression of effector cytokines IFNγ and TNFα in NK cells exposed to tumors and re-challenged with either PVR+ and PVR− K562 cells." (PMID 37345049, 2023). "In MC38 tumors, TAS-115 did not increase the tumor-infiltrating CD8+ T cells population, but increased IFNγ+CD8+ T cells and Gzmb+CD8+ T cells." (PMID 37258621, 2023). "Investigators have detected that the higher frequencies of IFNγ-producing CD4+ T cells and higher amount of secreted IFNγ before the induction treatment are characteristic of patients who do not show tumour recurrence at 6 months." (PMID 36928373, 2023). "In contrast to our findings in the tumor samples, we did not detect STING expression at baseline or after IFNγ stimulation in HD or E2 conditions in MCF7 cells." (PMID 37450351, 2023). "In contrast, IFNGR signaling in non-endothelial cells had the opposite effect of promoting tumor growth, consistent with the counter-regulatory production of IL6 elicited by IFNγ-mediated induction of IDO1." (PMID 37182174, 2023). "Strikingly, the anti-tumor activity of cGAMP in mouse colon cancer and melanoma was impaired in the absence of CD4 T cell-derived IL-9 or IFNγ." (PMID 37189417, 2023). "In fact, preliminary results of a gene expression analysis of fresh tumor tissue provided evidence that the mRNA levels of IL2, IFNG, IL6 and TNFA are increased in SGCT but not in NSGCT, which is in line with our cell culture data (unpublished results)." (PMID 37174085, 2023). "Local concentrations were not different between IFNγ–GFP and IFNγΔKRKR–GFP; however, we surmise that the ECM-bound IFNγ–GFP is less quantitatively extracted from the tumor tissue than IFNγΔKRKR–GFP." (PMID 36732425, 2023). "This tumor control requires IFNγ production by CD4 T cells, MHC-II expression on tumor cells, and is independent of host immune cells." (PMID 37185301, 2023). "In line, analysis of culture supernatants by Legendplex assays showed a significant increase in IL-2, IFNγ, IL-10 and TNF secretion after treatment with 1 nM CC-3, but not with the isotype control or when target antigen negative tumor cells were used." (PMID 37122707, 2023). "Nevertheless, we failed to observe the activation of tumor-specific CD4+ T cells which mainly function in coordinating the immune response and require strong and sustained activation to produce IFNγ." (PMID 37296221, 2023). "Unlike the tumor-reactive exhaustion module in MSI CRC, none of the specific subclusters of IFNG+CD8+ T cells in MSS CRC recruited IFNG, possibly indicating a lack of immunological orientation for IFNG51." (PMID 37968259, 2023). "In contrast, IL-12 and IFNγ producing DC and cytotoxic CD8+ T cells mediated anti-tumour immunity but were not necessary for tissue pathology." (PMID 35454819, 2022). "While tumour cells do not constitutively express MHC-II, IFNγ present in the tumour microenvironment can induce MHC-II in tumour cells (tsMHC-II)." (PMID 35343573, 2022). "It is a cis-acting lncRNA that gets stimulated by interferon-γ (IFNγ) and induces upregulation of major histocompatibility complex 1 (MHC-I) expression on tumour cells but does not affect PD-L1." (PMID 36230680, 2022). "Broadly, non-responders (high TIDE score) had significantly lower IFNG, Merck18, CD274 (PD-L1), CD8 and ‘dysfunction of the tumor’ scores." (PMID 36389735, 2022).
tumor (continued). "Addition of the TGFβRII inhibitor SB431542 to OT-I:ID8-OVA-T4 co-cultures doubled the proportions of IFNγ+granzyme B+ OT-I cells, but did not impact upon OT-I T cell responses to ID8-OVA-N4 tumour cells." (PMID 35958566, 2022). "RNAseq analyses indicated that the expression profile of IFNγ activated T cells differ markedly than that induced by anti-CD3 or LPS, which do not induce cell-in-cell formation in tumor cells." (PMID 36124553, 2022). "We found a significant difference between the two groups where the group showing a higher CD4 T-cell IFNγ expression had a lower tumor burden (responders) and the group with a lower CD4 T-cell IFNγ expression had a higher tumor burden (non-responders)." (PMID 35651802, 2022). "CD4 production of IFNγ, and not TNFα or CD40L, is required for the reeducation process and tumor rejection." (PMID 35903540, 2022). "(f, g) Linear correlation of proCAR oligomeric state vs. IFNγ, IL-2, TNFα, and GM-CSF cytokine production (normalized to CD28TM reference) from 24 hr co-culture with (e) MC57-HER2 and (f) antigen-negative MC57 tumor cells." (PMID 35506657, 2022). "Flow cytometry analysis of tumor-infiltrating cells demonstrated that cefepime increased dendritic cells, CXCR3+ CD8+ T cells (consistent with TH1-polarized immunity), and IFNγ+ NK cells, whereas rabusertib alone did not." (PMID 35563520, 2022). "Unlike MHC-I, PD-L1 was expressed on Y3.3UVRc34 but notably absent on YR1.7 tumor cells, consistent with the lack of PD-L1 expression on YR1.7 cells exposed to IFNγ in vitro; PD-L1 was expressed in the TME of both models." (PMID 36230753, 2022). "While this sensitizing effect is IFNγ(-R1)-dependent, it does not preclude the cell-intrinsic secondary effects of IFNγ signaling, such as MHC class I upregulation or any of the other anti-tumor effects that have been reported for IFNγ signaling." (PMID 35395848, 2022). "We also found that blocking either the PERK pathway or IFNγ inhibited PD-L1 upregulation and that PD-L1 expression on MDS cells did not inhibit their lysis by tumor-specific T cells." (PMID 35992887, 2022). "The expression of inflammatory cytokines, such as TNF-α, interferon-gamma (IFN-γ), IL-1, and IL-6, which act as anti-tumor effectors, did not vary between the sensitive and resistant groups." (PMID 35965549, 2022). "CD4+ TEG011_CD8α cells produced a significantly higher IFNγ level compared to CD4+ TEG011, which was equivalent to those of TEG011 bulk cells against all tumor targets, without affecting healthy cells." (PMID 34759930, 2021). "99LN‐BrM tumor cells alone did not significantly change T‐cell activity based on CD69, IFNγ, and Gzmb protein level." (PMID 33755340, 2021). "AH1-specific T cells, instead, produced IFNγ and TNFα both upon stimulation with beads and CT26, but not with F1F tumor cells." (PMID 33796916, 2021). "Thirdly, human T cell-secreted interferon gamma (IFNG), which is known to be important for tumor eradication, does not act on murine tumor stromal cells." (PMID 33801448, 2021). "For this purpose, the tumors raised in mice receiving SFV/IFNg, SFV/Luc, or PBS but no Pam3 were subjected to flow cytometry analysis to dissect the composition of tumor-infiltrating immune cells." (PMID 34835178, 2021). "Even in the absence of IFNγ, activation of the miR-200/ZEB1 axis resulted in induction of T cell exhaustion in mesenchymal tumor cells, evading immune recognition and attack." (PMID 34065396, 2021). "Nevertheless, the effector cytokine production capacity post peptide restimulation in the periphery and at the tumor site was comparable between the SCR and PGC-1α overexpression groups in terms of IFNγ, TNFα, granzyme B, and IL-2 production (data not shown)." (PMID 32055005, 2021). "PD-L1 can be expressed in metastatic UM cell lines in response to interferon-gamma (IFN-γ) and this phenomenon indicates a lack of activated T cells in MUM tumor microenvironment." (PMID 32050636, 2020).
tumor (continued). "Within the tumors, researchers found increased tumor specific CD8+ T cell infiltration and high levels of IFNγ and TNFα when compared to an adenovirus control and no treatment." (PMID 32499782, 2020). "Ablative RT combined with αPD-L1 mAb led to a significant increase in the number of CD8+ T cells expressing of IFNγ and Foxp3+ CD25+ expressing CD4+ T cells infiltrating into the tumor, but not into spleen or lymph nodes." (PMID 32287292, 2020). "After ruling out antigen loss on the tumor cells or lack of CAR-T cell infiltration into the tumor they observed that the CAR-T cells harvested from the tumor site had lost their cytotoxic potential in vitro (i.e., lack of IFNγ production)." (PMID 32325898, 2020). "If either TNFα or IFNγ signaling in tumor-infiltrating CD4+ T cells is absent upon antigen recognition, tumor progression is stimulated, whereas combined TNFα and IFNγ signaling in CD4+ T cells prevents tumor angiogenesis and tumor-cell proliferation." (PMID 32733461, 2020). "Ablative radiation significantly increased infiltration of CD8+ cells expressing IFNγ (CD8+ effector T-cell) and CD4+ CD25+ FOXP3+ (Treg) cells to the tumor while hypofraction and conventional RT did not." (PMID 32287292, 2020). "IL-12-transduced BMDCs were substantially more effective than IL-12-transduced fibroblasts or non-transduced BMDCs at inducing tumor-specific CTL activity and IFNγ production by draining lymph node cells and splenocytes." (PMID 33178203, 2020). "By contrast, surface markers of exhaustion (PD-1), activation (KLRG1, Granzyme B, perforin, Interferon gamma (IFNγ)) and death (CD95) were no different on tumor infiltrating CD8+ T cells between TM and vehicle treated mice." (PMID 32085796, 2020). "In tumor lysates, STAT1 phosphorylation was not consistent with the presence of M2-polarized macrophages or IFNγ suggesting that the constitutive activation of STAT1 was not related to the JAK–STAT pathway." (PMID 32642677, 2020). "No major differences were observed within the CD4+ tumor-reactive TILs, which appeared to be primarily characterized by tumor necrosis factor (TNF) production only, and a smaller population releasing both IFNγ and TNF." (PMID 33198174, 2020). "Protein levels of IL-10 and interferon-gamma cytokines did not significantly differ between LC–COPD and LC in either tumor or non-tumor lung specimens." (PMID 32414037, 2020). "Interestingly, we showed that active tumor cell lysis and IFNγ production were only detected in ex vivo cultures derived from larger tumors containing low PD-1+ TILs densities confirming the potential of these TILs to produce IFNγ when adaptive immune resistance has not yet occurred." (PMID 32642679, 2020). "Tumour cell lines SNU-5 and GTL-16 were not expressing PD-L2, neither under basal conditions nor upon IFNγ stimulation (data not shown)." (PMID 30723303, 2019). "In tumor-free cohorts, no CAR-T cell expansion was detected by flow cytometry, but low levels of IFNγ were detected on days 11 and 12 in animals that received the same number of CAR-T cells plus EC17." (PMID 30941303, 2019). "However, CD8+ T cells themselves are also promoted by IFNγ which could mean that if we reach a positive balance in the TME wherein the beneficial effects of IFNγ bridges the unfavourable effects of PD-L1, the net contribution may be an improved tumour surveillance." (PMID 30931254, 2019). "However, albeit the limited direct oncolysis, cytokines like IFNγ, TNFα and IFNβ, induced in the tumor tissue early after VSV‐GP treatment, are known to be able to induce apoptosis and may be involved in the increased caspase‐3 staining seen in the tumor tissue." (PMID 30972741, 2019). "(A) Pictures and analyses of (B) spheroid volume, (C) tumor cell apoptosis, and (D) spheroid infiltration 48h after coculturing HT29 spheroids with CD19-CD14- PBMCs in the presence or not of anti-IFNg blocking antibodies." (PMID 30871626, 2019).
tumor (continued). "We also preliminary attempted subcutaneous injection of B16F10 cells that we still found significantly increased tumor-infiltrating IFNγ and/or TNFα producing CD4 and CD8 T cells although tumor size was not reduced." (PMID 29403003, 2018). "In this study, we found that both of T cells and IFNγ production contribute to tumor growth inhibition induced by LNT treatments, whereas IFNγ, but not T cells, is required for the LNT-mediated antiangiogenic effect." (PMID 30373628, 2018). "Of note, non-suppressive tumor-infiltrating CD56bright ILCs were distinguished from regulatory CD56+ ILCs by a different gene expression profile and high production of IFNγ and TNFα in the absence of IL-22." (PMID 30454038, 2018). "Early experiments showed that treatment of mouse NK cells with anti-2B4 monoclonal antibody (mAb) led to increased IFNγ production and augmented non-MHC-restricted killing of tumor cells in vitro." (PMID 30546369, 2018). "In contrast, TGFβi NK cells maintain anti-tumor cytotoxicity against some cell lines (DAOY) and produce more IFNγ than NK cells cultured without TGFβ, suggesting that TGFβ in this system does not convert NK cells into ILC1s." (PMID 30400618, 2018). "The increase in local IFNγ in response to the combination of anti-CTLA-4 and PARPis was sufficient to inhibit tumor growth, but this combination had no such effect on BRCA1-sufficient ovarian cancer cells that were inoculated into the mice." (PMID 30487462, 2018). "Glucose-deprived T cells had impaired nuclear translocation of NFAT1 (but not NFAT2), which correlated with reduced IFNγ and CD40L expression and anti-tumor immunity." (PMID 29568499, 2018). "Distinct from IFNγ, type I IFN within innate immune system is critical for T cell priming and tumor elimination through signaling on DCs and lack of type I IFN will result in limited useful T cells for reactivating of antitumor activities." (PMID 30294272, 2018). "Infection of MDA-MB-231BR with RRV-miRGFP, a control RRV expressing a non-PDL1 target, does not affect PDL1 cell surface expression and, importantly, does not alleviate the tumor-dependent, PDL1-mediated immune suppression of IFNγ+ CD8+ T cells." (PMID 28325288, 2017). "This is consistent with the fact that IFNγ and CXCL9 messenger RNA levels are specifically increased in MT/Shc2F/2F tumours but not in MT/ShcA+/+ or MT/Shc313F/313F tumours." (PMID 28276425, 2017). "We also observed that none of these ligands were downregulated by IFNγ; however, CD274/PD-L1, CD54/ICAM-1, HLA-DR, MHC-class I, CD95/FasR, and CD270/HVEM were upregulated in a variety of tumor types." (PMID 28428785, 2017). "Therefore, the CD3xPDL1 BiTE may be effective in activating antitumor immunity against tumor cells that constitutively express low levels of PDL1 as well as in situations where there is already an active T cell-mediated antitumor immune response and IFNγ is driving the expression of PDL1." (PMID 28938530, 2017). "Data showed that TCP-1/IFNγ could colocalize with tumor vasculature, but not with blood vessels in normal organs including brain, heart and normal colon tissues, indicating that IFNγ protein did not negatively affect the binding ability of TCP-1 to tumor vasculature." (PMID 27342639, 2016). "Furthermore, even though repetitive administration of exogenous rmIFNγ with CY+TLRa enabled tumor rejection to occur in nude mice not receiving WT T-cells, such exogenous rmIFNγ could not replace the requirement for IFNγ-producing T-cells to achieve sustained tumor rejection." (PMID 27341020, 2016). "Taken together, these results suggested that GVAX therapy leads to an increased CD8+ T cell presence in the TME; however, it does not enhance the general IFNγ production in these CD8+ TILs, in spite of enhancing the tumor-specific IFNγ production." (PMID 26515728, 2015).